GTPBP6 (GTP binding protein 6 (putative) )
Synonyms: PGPL
Gene: Protein-coding gene on chromosome Y (303,346 to 318,846, reverse strand). Ensembl gene ENSG00000292358.
Gene Ontology:
Molecular function: ribosomal large subunit binding; GTP binding; ribosome binding
Biological process: mitochondrial large ribosomal subunit assembly
Cellular component: mitochondrion; cytoplasm
Diseases named in the same sentence as GTPBP6 in open-access papers:
GTPBP6 is named in the same sentence as 4 diseases in open-access papers, as found by Europe PMC text mining. Sharing a sentence is not in itself a finding about the gene and the disease. The quoted sentences say what the papers report.
Klinefelter syndrome (2 papers, 2020 to 2021). A sex chromosome disorder caused by the presence of an extra X chromosome in the male karyotype. "In contrast, human GTPBP6 is probably expressed constitutively in all tissues and its expression must be tightly controlled, as abnormally high GTPBP6 levels in lymphoblasts have been associated with language impairment in men with Klinefelter's syndrome." (PMID 33264405, 2020).
Alzheimer disease (1 paper, 2021). A progressive, neurodegenerative disease characterized by loss of function and death of nerve cells in several areas of the brain leading to loss of cognitive function such as memory and language. "Therefore, we speculate that MTUS2, GTPBP6, TIAM-1 and SHROOM2 are likely associated with Alzheimer’s disease." (PMID 33525573, 2021).
cognitive deficits (1 paper, 2025). "GTPBP6 expression, for instance, negatively correlates with IQ, especially in individuals with random XCI patterns, while skewed XCI patterns result in milder cognitive deficits." (PMID 40018421, 2025). "Normally, XCI balances gene dosage, but in KS, genes such as GTPBP6 (guanosine triphosphate binding protein 6), EIF2S3 (eukaryotic translation initiation factor 2 subunit 3), and KDM5C (Lysine(K)‐specific demethylase 5C) escape inactivation and are overexpressed, contributing to cognitive deficits." (PMID 40018421, 2025).
GTPBP6 also shares sentences with these, for which no sentence is quoted: dyschondrosteosis (1 paper).